PIK3R2 (phosphoinositide-3-kinase regulatory subunit 2)
Diseases named in the same sentence as PIK3R2 in open-access papers (continued):
Sharing a sentence is not in itself a finding about the gene and the disease.
colon carcinoma (10 papers, 2011 to 2025). "Normal cells express higher levels of PIK3R1 (which encodes p85α) than of PIK3R2 (p85β); in contrast, metastatic melanoma, invasive breast cancer and advanced colon carcinoma show a marked increase in PIK3R2 expression, which correlates with tumor grade." (PMID 27835880, 2016). "Finally, although it was unknown whether depletion of p85β in an already developed tumor might induce tumor regression, pik3r2-deficient mice exhibit reduced colon cancer formation whereas p85β overexpression accelerated tumor progression in the mouse." (PMID 27835880, 2016). "In breast and colon cancers PIK3R2 overexpression correlates with tumor grade." (PMID 27835880, 2016). "However, PIK3R2 has been shown to be an oncogene in breast and colon cancer and its induced overexpression of PIK3R2 correlates with PI3K pathway activation and tumor progression in vivo." (PMID 27191494, 2016). "Indeed, the oncogenic role of PIK3R2 has been demonstrated in breast and colon cancer, in which over-expression of PIK3R2 with concomitant AKT activation correlated with tumor progression in vivo." (PMID 26517243, 2015). "In addition, abnormal activation of the EPHA2 receptor may promote the development of nasopharyngeal cancer, gastric cancer, and colon cancer, whereas PIK3R2 localizes to the cytosol and also concentrates at focal adhesions as well as in the nucleus." (PMID 34484860, 2021).
hepatocellular carcinoma (9 papers, 2014 to 2026). A malignant tumor that arises from hepatocytes. "Furthermore, miRNA-126-3p reduces LRP6 and PIK3R2,59, which decreases angiogenesis in hepatocellular carcinoma (HCC)." (PMID 36765409, 2023). "MiR-126-3p can target PIK3R2 to suppress metastasis and angiogenesis in hepatocellular carcinoma." (PMID 27729613, 2016). "PIK3R2 has been considered vital in some malignancies and reported as the target of several microRNAs, such as miR-126 in esophageal squamous cell carcinoma, miR-126-3p in hepatocellular carcinoma, and so forth." (PMID 27467251, 2016). "MiR-126-3p was reported to suppress tumor metastasis and angiogenesis of hepatocellular carcinomas by targeting LRP6 and PIK3R2, and its restoration may be a promising strategy for HCC therapy." (PMID 29685146, 2018). "Similarly, downregulated miR-126-3p also fails to suppress tumor metastasis and angiogenesis of hepatocellular carcinoma by its reduced ability to repress LRP6 and PIK3R2 expression." (PMID 38256049, 2024).
diabetes (7 papers, 2019 to 2023). "TP73, PIK3R2, SLC9A3R1, KRT5, KRT14 and TFAP2C are novel biomarkers for pathogenesis of obesity associated type 2 diabetes mellitus." (PMID 33902539, 2021). "One of the miRNAs most strongly linked to diabetes was miR-126, which was abundant in endothelial cells and helped maintain their health and the integrity of blood vessels by suppressing negative regulators of the VEGF pathway, such as SPRED1 and PIK3R2/p85-β." (PMID 38067127, 2023). "The hub genes CEBPD, TP73, ESR2, TAB1, MAP 3K5, FN1, UBD, RUNX1, PIK3R2 and TNF, which might play an essential role in obesity associated type 2 diabetes mellitus was further screened." (PMID 33902539, 2021). "In the insulin receptor signaling pathway, PIk3R2 is an important regulatory subunit of PI3K/p85, and it can significantly suppress the activation of the PI3K/Akt pathway participating in the physiological and pathological diabetes processes." (PMID 34084770, 2021). "Further correlation analysis indicated the key molecules involved in PI3K-AKT signaling pathway, such as AKT1, AKT2, PIK3R1, and PIK3R2, showed significant positive correlations with AFAP1L2, and in which AKT1 also showed elevated expression in patients without diabetes history." (PMID 36434634, 2022).
endometrial cancer (6 papers, 2017 to 2022). Primary or metastatic malignant neoplasm involving the endometrium (mucous membrane that lines the endometrial cavity). "A piece of supporting evidence is that a pathogenic variant of PIK3R2 (c.1681 A > G; p.Asn561Asp) was found to cause endometrial cancer, which indicate that mutations in the same gene could result in quite distinct phenotypes." (PMID 34040629, 2021). "Established evidence proves that co-mutations in PIK3R1 and PIK3R2, the members of PI3K-Akt signaling pathway, are mainly involved in the development of endometrial cancer." (PMID 35893039, 2022).
Insulin resistance (6 papers, 2015 to 2024). Increased resistance towards insulin, that is, diminished effectiveness of insulin in reducing blood glucose levels. "PIK3R1, PIK3R2, and PIK3CA, encoding the p110α catalytic subunit, were next sequenced in 262 further probands with severe insulin resistance." (PMID 27766312, 2016). "The regulatory role of PIK3R2 was reported as ameliorating insulin sensitivity in PIK3R2 knockout mice, while a promoter variant of PIK3CB is reported to provide protection from insulin resistance in obese and non-obese individuals." (PMID 33669862, 2021).
polymicrogyria (6 papers, 2017 to 2023). A developmental brain abnormality characterized by an excessive amount of small convolutions on the surface of the brain and cognitive dysfunction. "Pik3r2 mutations have also been observed to cause polymicrogyria, corpus callosum hyperplasia, and focal cortical dysplasia." (PMID 34630032, 2021). "PIK3R2 was associated with Megalencephaly-Polymicrogyria-Polydactyly-Hydrocephalus32, although the molecular details of the disease were not revealed yet (bottom, right)." (PMID 33060664, 2020). "However, individuals with polymicrogyria and documented macrocephaly had variants only in genes encoding components of or related to the mTOR pathway (PIK3R2, PI3KCA, AKT3, and PTEN)." (PMID 37486637, 2023). "Concordant with prior literature, the most common genetic etiologies we found for polymicrogyria were in the PIK3R2 (9 families) and TUBB2B (6 families) genes." (PMID 37486637, 2023). "Regarding head MRI findings, enlargement of the ventricle, polymicrogyria, and white matter abnormalities were observed in all patients with AKT3 or PIK3R2 mutations, and seemed indicative of mTOR pathway involvement." (PMID 28086757, 2017). "Regarding brain MRI findings, while ventriculomegaly, polymicrogyria and white matter abnormalities were observed in all patients with AKT3 and PIK3R2 mutations, no obvious abnormalities were found in patients with PTEN mutations." (PMID 28086757, 2017).
colorectal cancer (5 papers, 2015 to 2025). A primary or metastatic malignant neoplasm that affects the colon or rectum. "Additionally, PIK3R1 and PIK3R2 were found to be hypermethylated, specifically in lung and colorectal cancers, respectively." (PMID 33143142, 2020).
gastric cancer (5 papers, 2013 to 2022). A primary or metastatic malignant neoplasm involving the stomach. "Though not previously implicated in GBC, CHD1 is a known gastric cancer driver and PIK3R2 is frequently mutated in endometrial cancers." (PMID 32839463, 2020). "In gastric cancer tissues, miR-126 can also directly inhibit VEGF signaling pathways, including expression of PIK3R2 and p85-b, thereby playing a role in anti-angiogenesis and inhibition of vascular integrity." (PMID 24350576, 2013).
megalencephaly (5 papers, 2015 to 2023). A congenital abnormality in which the occipitofrontal circumference is greater than two standard deviations above the mean for a given age. "Mutations of PIK3R2, encoding the p85β regulatory subunit of PI3K, have shown the ability to augment PI3K signaling, which has been perceived in patients with hypoglycemia and either segmental overgrowth or megalencephaly." (PMID 37664840, 2023).
Obesity (5 papers, 2021 to 2023). Accumulation of substantial excess body fat. "Expression of phosphoinositide-3-kinase regulatory subunit 2 (PIK3R2) and Reduced nicotinamide adenine dinucleotide phosphate (NADPH) quinone oxidoreductase 1 (NOQ1) genes was increased in obesity and COPD, respectively, compared with the controls." (PMID 37886639, 2023). "We also observed an upregulation of PIK3R2 in COPD and obesity." (PMID 37886639, 2023).
rheumatoid arthritis (5 papers, 2016 to 2023). A chronic, systemic autoimmune disorder characterized by inflammation in the synovial membranes and articular surfaces. "In rheumatoid arthritis synovial fibro-blasts cell, PIK3R2 inhibited the proliferation and promoted the apoptosis by regulating PI3K/AKT pathway." (PMID 31480138, 2020). "The result was in accordance with previous study where they found that knockdown PIK3R2 could inhibit the apoptosis and promote the proliferation of rheumatoid arthritis synovial fibro-blasts cell." (PMID 31480138, 2020).
cervical cancer (4 papers, 2019 to 2025). A primary or metastatic malignant neoplasm involving the cervix. "The molecular docking analysis of the 306 differential proteins with known cervical cancer–related targets identified intersecting proteins within the PI3K/AKT signaling pathway: PIK3R2, GRB2, MAPK1, FGF2, and PRKCA." (PMID 40733070, 2025). "Our study showed that PIK3R2 expression is also upregulated in cervical cancer which eventually proceeds to distant recurrent disease." (PMID 35087740, 2021). "Similarly, PIK3R2 upregulation has been observed in cervical cancer, ultimately contributing to distant recurrence." (PMID 40733070, 2025). "Measuring the expression of GLS and PIK3R2 in the resected cervical cancer samples may be a future step in the identification of patients with a high risk of recurrence." (PMID 35087740, 2021). "The expression of seven hub genes in the PI3K/AKT/mTOR pathway were increased in cervical cancer: EIF4EBP1, GSK3B, HRAS, KRAS, NRAS, PIK3CB and PIK3R2." (PMID 36911370, 2023). "Various genes, namely GLS, CD36, WNT5a, HRAS, DDB2, PIK3R2, and CDH2 were found to be differentially highly expressed in primary cervical cancer samples of patients who developed distant recurrence." (PMID 35087740, 2021). "Namely, GLS, CD36, WNT5a, HRAS, DDB2, PIK3R2, and CDH2 were significantly DE between cervical cancer without recurrence and cervical cancer with distant recurrence." (PMID 35087740, 2021).
glioma (4 papers, 2023 to 2025). A benign or malignant brain and spinal cord tumor that arises from glial cells (astrocytes, oligodendrocytes, ependymal cells). "Additionally, our data demonstrated a positive correlation between NAT10 and PIK3R2 in glioma patients." (PMID 41408025, 2025).
lung squamous cell carcinoma (4 papers, 2016 to 2022). "Higher expression PIK3R2 has been observed in lung squamous cell carcinoma as compared to normal tissue." (PMID 29755656, 2018).
prostate carcinoma (4 papers, 2015 to 2023). A carcinoma that arises from epithelial cells of the prostate gland. "Together, our results suggest that ARID4B and HDAC1 are likely to function independently to regulate PIK3CA and PIK3R2 in prostate cancer cells." (PMID 31551414, 2019). "To determine the functional significance of our findings that ARID4B is a transcriptional activator of the PI3K subunits PIK3CA and PIK3R2, we investigated the role of ARID4B in the development of prostate cancer harboring PTEN deficiency." (PMID 31551414, 2019). "Furthermore, PIK3R2 upregulation in prostate cancer specimens has recently been shown to inversely correlate with miR-126 expression." (PMID 32630372, 2020). "Song and colleagues identified PIK3R2 as a direct target of miR-126 in prostate cancer cell lines, and reported that enforced miR-126 expression in prostate cancer cell lines reduces PIK3R2 mRNA expression and suppresses cell proliferation, migration, and invasion." (PMID 32630372, 2020). "In prostate cancer, especially in the PTEN-null phenotype, upregulation of ARID4B activates the PTEN-PI3K pathway through specific transactivation of both PIK3CA and PIK3R2, which favors tumor progression and correlates positively with prostate cancer recurrence." (PMID 38137006, 2023). "A prostate cancer related module was investigated (due to its significant enrichment on KEGG prostate cancer pathway), which has DEGs as PDGFRB, PDGFB, SNX2, EGFR and DECGs as (PDGFRA, PDGFRB), (SNX4, PDGFRB), (PDGFB, PDGFRA), (SNX2, PDGFRA), (PDGFRB, PIK3R2), (EGFR, PIK3R2), (EGFR, AREG)." (PMID 26070628, 2015).
cardiac hypertrophy (3 papers, 2021 to 2025). "PIK3R2 is a potential target gene for miR-126a-3p, which has been extensively studied in tumors and has also been reported in myocardial hypertrophy and LPS-induced sepsis ALI." (PMID 41293091, 2025). "AA up-regulated the expression of miRNA-126, which is markedly down-regulated in an AngII-induced model of cardiac hypertrophy; the study revealed that miR-126 directly targets PIK3R2, as shown by the inverse relationship between the concentrations of miR-126 and PIK3R2." (PMID 35887090, 2022). "In this study, we arrived at a conclusion that miR-126 targeting PIK3R2 activating the PI3K/AKT signaling pathway, and promoted cardiac hypertrophy and fibrosis in AngII-induced rats." (PMID 34256802, 2021). "The up-regulation of miR-126 by AA induces a reduction of PIK3R2, which in turn triggers the inhibition of the PI3K/Akt signaling pathway, thus providing cardio-protection; overall, AA may act as potential preventive agent against cardiac hypertrophy and fibrosis." (PMID 35887090, 2022).
Familial Temporal Lobe Epilepsy (3 papers, 2021 to 2025). "Interestingly, a mutation of Pik3R2 was associated with familial temporal lobe epilepsy, and its overexpression may reduce cell viability and boost autophagy and apoptosis." (PMID 40699779, 2025). "Expression of PIK3R2 in the resected brain tissue of patients with refractory temporal lobe epilepsy was also significantly higher than that in a non-epileptic control group." (PMID 34040629, 2021). "Finally, pathological testing of the resected temporal lobe cortex showed that the expression of PIK3R2 was significantly higher in patients with refractory temporal lobe epilepsy than in those of non-epileptic diseases as a control group." (PMID 34040629, 2021).
Glucose intolerance (3 papers, 2016 to 2021). Glucose intolerance (GI) can be defined as dysglycemia that comprises both prediabetes and diabetes. "Inhibition of class IA PI3K via knockout of pik3r1 and pik3r2 genes in mice led to a decrease in insulin secretion and increased glucose intolerance, suggesting that class IA PI3K in β-cells is important for maintaining intracellular Ca2+ levels and cell-cell synchronization." (PMID 28856166, 2017).
liver cancer (3 papers, 2021 to 2023). An epithelial or non-epithelial malignant neoplasm that arises from the liver. "Besides, PIK3R3 displayed a more pronounced variation in liver cancer compared to normal tissues, in contrast to PIK3R1 and PIK3R2.In fresh clinical samples, we confirmed that PIK3R3 was overwhelmingly upregulated in HCC compared with paired normal tissues." (PMID 37212524, 2023).
Ventriculomegaly (3 papers, 2017 to 2021). An increase in size of the ventricular system of the brain. "Conversely, PIK3R2 cases usually show only ventriculomegaly and milder cognitive impairment." (PMID 35096710, 2021).
Brain Malformation (2 papers, 2015 to 2024). "Gene-specific recommendations were recently reported for PIK3R1, and for AKT3, MTOR, PIK3CA and PIK3R2 by the ClinGen Brain Malformation Variant Curation Expert Panel." (PMID 38778413, 2024). "Variants in PI 3-kinases and their regulatory subunits, PIK3CA, PIK3R2 as well as one of their downstream targets, AKT3, have all been implicated in PMG and associated brain malformation phenotypes." (PMID 25855803, 2015).
breast invasive carcinoma (2 papers, 2016 to 2022). "Furthermore, the expression of both PIK3R1 and PIK3R2 was associated with the level of immune infiltration in multiple tumors, such as breast invasive carcinoma." (PMID 35395865, 2022).
endothelial dysfunction (2 papers, 2018 to 2020). In vascular diseases, endothelial dysfunction is a systemic pathological state of the endothelium (the inner lining of blood vessels) and can be broadly defined as an imbalance between vasodilating and vasoconstricting substances produced by (or acting on) the endothelium. "Since miR-126 facilitates VEGF signaling by repressing SPRED1 and PIK3R2/p85-β, it has been suggested that low plasma miR-126 levels might have an impact on VEGF resistance and endothelial dysfunction in patients with T2DM." (PMID 29615970, 2018).
esophageal squamous cell carcinoma (2 papers, 2016 to 2017). Esophageal squamous cell carcinoma (ESCC) is a type of esophageal carcinoma (EC) that can affect any part of the esophagus, but is usually located in the upper or middle third. "In addition, PIK3R2 overexpression was noted in esophageal squamous cell carcinoma, and is thought to be related to under-expression of microRNA-126, which likely plays a tumor-suppressing role and targets PIK3R2." (PMID 28108737, 2017).
lung adenocarcinoma (2 papers, 2020 to 2022). A carcinoma that arises from the lung and is characterized by the presence of malignant glandular epithelial cells. "Superior CAPN1 and inferior PTPN1 were related to activation of c‐Met/PIK3R2 in lung adenocarcinoma." (PMID 32395869, 2020).
ovarian tumor (2 papers, 2020 to 2022). "Together, these findings suggest that therapeutic blockade of AXL signaling may be an effective strategy for ovarian tumors with PIK3R2 amplification." (PMID 32385243, 2020). "This kinase-substrate regulatory mode between FER and IRS4, which leads to PIK3R2 recruitment and AKT activation, is critical for ovarian tumor cell growth." (PMID 35550247, 2022).
acute leukemia (1 paper, 2022). A clonal (malignant) hematopoietic disorder with an acute onset, affecting the bone marrow and the peripheral blood. "We also demonstrated that KMT2A-r acute leukemia patients overexpress three genes (ALDH3A1, PIK3R2, and TYMP) with interaction annotation to 5-Fluorouracil." (PMID 35734412, 2022).
adenoma (1 paper, 2022). A neoplasm arising from the epithelium. "The results also included previously unreported genes including AKT3, NCOR2, PIK3R2, SMAD4, and TGFBR1, from which AKT3 and PIK3R2 were present in the early adenoma stage and SMAD4 and TGFBR1 were present at the late adenoma stage." (PMID 36499586, 2022). "These genes were involved in different stages of cancer development as analyzed using the KEGG pathway, this includes SMAD4 and TGFBR1 at the late adenoma, and AKT3 and PIK3R2 at the carcinoma stage in CRC development." (PMID 36499586, 2022).
brain tumors (1 paper, 2021). "This is consistent with studies of PIK3CA variants in brain tumors and mouse models with patient-related Pik3r2 mutations, which are less common causes of intractable epilepsy." (PMID 34899181, 2021).
Cerebral ischemia (1 paper, 2024). Restriction of arterial blood supply to the brain associated with insufficient oxygenation to support the metabolic requirements of the tissue. "MiR-199a-5p alleviated BBB damage, suppressed inflammatory reaction, and neuron damage caused by cerebral ischemia by inhibiting PIK3R2 and activating Akt." (PMID 39302945, 2024).
developmental delays (1 paper, 2017). "While developmental delays were observed in all patients, patients with AKT3 or PIK3R2 mutations had no meaningful words and had a more severe disease phenotype than those with PTEN mutations." (PMID 28086757, 2017).